RN7SL342P (RNA, 7SL, cytoplasmic 342, pseudogene)
Gene: Miscellaneous RNA gene on chromosome 18 (59,972,914 to 59,973,207, forward strand). Ensembl gene ENSG00000239398.
Homologues: Orthologues: chimpanzee Metazoa_SRP (97% identical), macaque Metazoa_SRP (88% identical). Paralogues in human: RN7SL1 (85% identical), RN7SL2 (85% identical), RN7SL3 (84% identical), RN7SL126P (80% identical), RN7SL566P (80% identical), RN7SL448P (80% identical), RN7SL45P (80% identical), RN7SL478P (80% identical), RN7SL47P (80% identical), RN7SL597P (80% identical), RN7SL678P (80% identical), RN7SL230P (79% identical), and 703 more.